LEP (leptin)
Diseases named in the same sentence as LEP in open-access papers (continued):
Sharing a sentence is not in itself a finding about the gene and the disease.
Obesity (continued). "Fourth, considering the model of obesity used (Zucker rat), it would have been interesting to determine the plasma level of leptin." (PMID 30964881, 2019). "In patients with obesity and diabetes there was approximately 1.3-fold higher protein expression of leptin, and ~ 1.7-fold higher protein expression of IL-6 in SAT, as compared to non-obese controls." (PMID 31533725, 2019). "Leptin has been acknowledged to be a critical element of the obesity-related progression and malignancy of breast cancer." (PMID 31616626, 2019). "The impact of obesity and its effects on human health have increased at very high rates over recent years since the discovery of leptin." (PMID 31717265, 2019). "Next, relationships between serum adiponectin/leptin (A/L) ratio and clinical parameters were evaluated because adiponectin and leptin show vastly different serum concentrations in obesity and opposite effects on PPARγ expression." (PMID 31324858, 2019). "Aberrant activation of these key hypothalamic intrinsic pathways likely impedes neural actions of leptin and central regulation of food intake and body weight, ultimately leading to obesity." (PMID 31403469, 2019). "Leptin concentrations also strongly correlate with adiposity, resulting in higher concentrations in obesity." (PMID 31262340, 2019). "The adipokine, leptin is strongly accumulated in obesity and promotes the development of breast tumors." (PMID 31398937, 2019). "This was expected as leptin is produced by adipocytes and patients with obesity are often leptin resistant." (PMID 31601900, 2019). "Adiponectin increased the intracellular Ca2+ release by colostrum phagocytes in the obesity group, whereas this was decreased by leptin." (PMID 31146419, 2019). "Adipokines such as leptin and resistin have been found to be consistently increased in both adults and children with obesity and the MS, contributing to insulin resistance." (PMID 31404407, 2019). "Leptin is closely correlated with obesity, which forms a sense of satiety in the brain and reserves energy in peripheral tissues via leptin receptor (LepR)." (PMID 30800100, 2019). "In diet-induced obesity the hypothalamic leptin and insulin signaling is largely changed, and these changes are the result of hormonal dysregulations and metabolic dysfunctions." (PMID 30870482, 2019). "This suggests that in a state of obesity, leptin accumulation is maintained in the key areas of the brain involved in metabolism and weight control." (PMID 31717265, 2019). "In particular, the relevance of insulin in the regulation of leptin levels and involvement in insulin downstream signaling indicates the key role of leptin in obesity-induced IR, which is under the thorough consideration of scientists." (PMID 31408957, 2019). "In both rodents and humans, leptin resistance plays a central role in the development of obesity, and leptin sensitizers have drawn much attention with the aim to ameliorate obesity and insulin resistance." (PMID 31509948, 2019). "In obesity, there is an expansion of white adipose tissue which is the primary site that produces adipokines such as leptin, resistin, and adiponectin." (PMID 31316526, 2019). "Using the HFD-induced obese mouse model, we observed a chronic excess of the basal plasma norepinephrine along with increasing plasma leptin levels during obesity development." (PMID 31682617, 2019). "First reports about leptin focused on its role in overweight and as a potential goal for obesity therapy." (PMID 30806766, 2019). "Molecularly, we found that leptin, an obesity hormone, showed a significant upregulation after krasG12V induction." (PMID 30718259, 2019). "The Nrf2 activity suppressed the hypothalamic oxidative stress, resulting in the improvement of the resistance of insulin and leptin related to obesity." (PMID 31817423, 2019).
Obesity (continued). "The mechanisms involved in leptin transportation across the blood–brain barrier continue to be unclear, thereby preventing the clinical application of leptin in the treatment of obesity." (PMID 31717265, 2019). "Sustained high leptin levels, in cross-talk with insulin resistance, have previously been related to obesity progression." (PMID 31873127, 2019). "Another possible explanation is that obesity is, in fact, protective against cognitive impairment due to the excess of leptin, a hormone involved in obesity pathogenesis and also related to memory and learning." (PMID 31133846, 2019). "The aim of the present study was to investigate the role of leptin as a possible mediator for the correlation between obesity and cardiovascular dysfunction by investigation of its direct influence upon the functioning human myocardium." (PMID 31019683, 2019). "Leptin, an adipokine regulating body fat mass, represents a key molecule in obesity, able to modulate immune responses and foster chronic inflammatory response in peripheral tissues." (PMID 31091785, 2019). "We report an increase in plasma leptin and a decrease in plasma adiponectin levels in patients with obesity or diabetes." (PMID 31533725, 2019). "The PCS also highlighted several other highly scoring candidates with known causal roles in relation to diabetes and obesity such as MC4R (PCS = 0.43), WFS1 (0.41), ABCC8 (0.37), LEP (0.27), GCK (0.24) and HNF1A (0.23)." (PMID 30914061, 2019). "In obesity condition, it is observed a disbalance on this secretion, where a greater release of pro-inflammatory cytokines (Leptin, IL-6, TNF-α among others) is seen in detriment to anti-inflammatory cytokines (Adiponectin and IL-10)." (PMID 31749764, 2019). "Leptin, a 16 kDa peptide hormone encoded by LEP gene (an obesity gene) and a nutritional cytokine, is closely related to cancer." (PMID 31119158, 2019). "Leptin which was identified as a product of obesity (ob) gene is an important member of this adipocytokine family." (PMID 31975995, 2019). "Mice BDNF conditional KO in brain, beside the metabolic phenotype (hyperphagia, increased abdominal AT, obesity, leptin resistance), displayed increased femur length, high BMD and BMC." (PMID 30792697, 2019). "Low gainers are resistant to diet-induced obesity and remain sensitive to the anorectic actions of leptin." (PMID 31143766, 2019). "Leptin levels have been shown to increase with age, and some have argued that ageing, along with obesity, constitutes a state of leptin resistance." (PMID 31751856, 2019). "For instance, maternal pre-pregnancy obesity increases circulation of glucose, lipids, leptin, and others." (PMID 31685839, 2019). "Collectively, these findings and the present results suggest that leptin contributes to the obesity-induced increased trabecular bone mass presumably through peripheral action." (PMID 31648235, 2019). "Leptin, an adipokine that normally inhibits hunger but exhibits resistance in obesity, was significantly increased in the HFD group compared to the lean group." (PMID 31196172, 2019). "Leptin levels are correlated with obesity-related diseases such as myocardial infarction and cerebral stroke." (PMID 31208019, 2019). "Leptin, a hormone that is capable of effectively reducing food intake and body weight, was initially considered for use in the treatment of obesity." (PMID 31717265, 2019). "The first genetic studies on obesity involved monogenic and extreme obesity syndromes, and the researchers focused their attention on the dysfunction of the leptin-hypothalamus pathway." (PMID 31341224, 2019). "These alterations in fat deposition and hypothalamic circuitry lead to metabolic complications in the adult, often in the form of obesity, as a direct result of phenotypes such as hyperphagia, reduced energy expenditure and leptin resistance." (PMID 31270580, 2019). "Decreased plasma levels of adiponectin, but increased levels of leptin were found in patients with obesity." (PMID 31533725, 2019).
Obesity (continued). "Obesity mediates its effect on cancer progression via dysregulation of adipocytokines including increased production of oncogenic adipokine leptin along with decreased production of adiponectin." (PMID 31121868, 2019). "The ability of boosting the leptin level and reducing the lipid metabolism by the high-dose spirulina implicates the potential therapeutic application for clinical obesity management." (PMID 31334136, 2019). "Within CRS obesity-prone subgroups, plasma leptin level was significantly elevated in the FX obesity-prone subgroup compared to the CS obesity-prone subgroup (P < 0.05)." (PMID 30664741, 2019). "In obesity, the leptin concentration increases, and it crosses the blood-brain barrier to regulate the endocrine system through actions in the arcuate nucleus of the hypothalamus." (PMID 31174521, 2019). "Leptin and LEPR mutations are associated with early onset severe obesity, severe hyperphagia and some neuroendocrine abnormalities, such as hypogonadotropic hypogonadism, impaired growth hormone secretion and hypothalamic hypothyroidism." (PMID 30991789, 2019). "Leptin gene overexpression in adipocyte and elevation of circulating leptin levels can also contribute to enhanced basal lipolysis in obesity due to its action on the leptin receptor." (PMID 31284400, 2019). "Adiponectin and leptin are adipokines produced from adipose tissue and are related to obesity and emaciation." (PMID 31324858, 2019). "Mutations in the leptin/melanocortin pathway (OB, LEPR, POMC, PCK1, MC4R) are associated with obesity in rodents and humans." (PMID 31500090, 2019). "Rodent studies showed that oral administration of leptin during the entire lactation period was beneficial for neonate rats by protecting them from obesity and overweight." (PMID 31408957, 2019). "The strong relationship found between obesity and depression led the way to explore the potential role of fat tissue in the cause of MDD through its production of leptin hormone." (PMID 31354416, 2019). "These adipokines levels are important indicators for the development of obesity and metabolic syndrome, since there is a reduction in the endogenous concentrations of adiponectin and an increase in leptin levels in overweight and obese individuals." (PMID 31146419, 2019). "They produce a range of adipokines, including leptin and adiponectin, which are known to correlate with obesity." (PMID 31311115, 2019). "Although the secretion of the chemokines KC/CXCL1 and MCP-1/CCL2 remained unchanged in 3T3-L1, our results show that leptin's actions on adipocytes contribute to the inflammatory profile characteristic of obesity." (PMID 31920961, 2019). "Leptin, adiponectin and miRNA showed a decrease over time of lactation in normal-weight mothers that was altered in overweight/obesity." (PMID 31661820, 2019). "Recently, an increased tumor incidence and aggressiveness along with elevated leptin/leptin receptor expression and signaling activation were found in mammary tissues of rat model of breast cancer driven by western diet-induced obesity." (PMID 30634494, 2019). "For studies on obesity, not only the BMI should be taken into account, but also the percentage of visceral adipose tissue and leptin levels in blood should be assessed." (PMID 31340438, 2019). "Disruption of this signaling axis as a result of insulin or leptin resistance is expected to upset the balance of fat and glucose regulation and contribute to the pathology of obesity and diabetes." (PMID 31151172, 2019). "In 2008, Nave and colleagues confirmed a role for leptin in the regulation of NK cells, and proposed a mechanism through which resistance of leptin signalling in NK cells underpinned their dysfunction in murine models of obesity." (PMID 31018563, 2019). "In the present study, we investigated GIP secretion in two mouse models of obesity: High-fat diet-induced obese (DIO) mice and leptin-deficient Lepob/ob mice." (PMID 31509948, 2019).
Obesity (continued). "A previous study identified an obesity-induced long noncoding RNA (lncRNA), lnc-leptin, which regulates adipocytes differentiation through the maintenance of leptin expression." (PMID 31109074, 2019). "Pro-inflammatory adipokines such as leptin, Tumor Necrosis Factor-alpha (TNF-α), interleukin (IL)-6, IL-1, IL-8, and resistin are increased in obesity and are associated with insulin resistance, type 2 diabetes and cardiovascular disorders." (PMID 31475003, 2019). "The plasma level of leptin is elevated in both obese and psoriatic individuals, and the elevated concentration is positively correlated with BMI and PASI scores, suggesting an important role of leptin in linking psoriasis and obesity." (PMID 31521168, 2019). "Literature alludes to several difficulties in conceptualizing the term “leptin resistance”, its temporal effects on obesity, as well as confirmatory laboratory tools to measure it in patients." (PMID 31557979, 2019). "Furthermore, an increased P. mirabilis abundance was observed in rats that underwent a high-fat diet, also being significantly correlated with triglyceride levels, and leptin and insulin concentration, indicating that this bacterium may be associated with low-grade inflammation linked to obesity." (PMID 30641996, 2019). "As a result, appetite is suppressed, and energy expenditure is enhanced hence mediating leptin’s anti-obesity effect." (PMID 31319588, 2019). "Both diet-induced obesity and models of genetic obesity show increases in serum leptin, concurrently with increased tumor growth and metastasis in murine models of pancreatic cancer." (PMID 31835454, 2019). "Low serum adiponectin and high serum leptin levels are considered as risk factors for developing type 2 diabetes (T2DM), obesity, dyslipidemia, hypertension, and cardiovascular diseases." (PMID 31398785, 2019). "Leptin/adiponectin ratio is highly induced in breast cancer, and more interestingly, the ratio correlated to the level of obesity." (PMID 31398937, 2019). "Leptin is an adipostatic hormone expressed by adipocytes to regulate adipose mass in mammals, and inhibition of leptin signaling leads to obesity or diabetes." (PMID 30718259, 2019). "Hypercorticism is oftentimes observed in obesity, and glucocorticoids are known to restrain the effects of leptin." (PMID 31877943, 2019). "Obesity also affects breast cancer in women by secretion of some adipokines, which are also called as “released hormones”, especially estrogen, adiponectin, leptin, and insulin." (PMID 31398937, 2019). "We also found a differing time course for the development of H‐reflex hyperexcitability and increased serum leptin levels between males and females, which is suggestive of sex differences in the progression of obesity‐related changes." (PMID 31660698, 2019). "Obesity-related insulin resistance, leptin and lactone levels are closely related to the occurrence and development of endometrial cancer." (PMID 31440472, 2019). "The AMPK pathway also includes CD36, an important regulator of cell adhesion and FA transport, and LEP gene, a major regulator of energy homeostasis, whose transcription, as expected, was up-regulated in obesity." (PMID 30838002, 2019). "Leptin is not only increased in obesity, but also found to be increased in patients with psoriasis, positively correlating with increasing severity of disease." (PMID 31316526, 2019). "At this time, the worldwide impact of leptin on the treatment of human obesity is limited to ∼25 individuals who receive it for congenital leptin deficiency, in whom it continues to work extremely well." (PMID 30357355, 2019). "Obesity is a pathological state associated with dysregulated inflammatory and metabolic mediators, including blood glucose, insulin, IGF-1, and leptin." (PMID 31835454, 2019). "Since obesity and dementia were related, many studies tried to find a link between brain leptin activity and AD development." (PMID 31191220, 2019).
Obesity (continued). "Recent studies have found that abnormal expression of leptin and leptin receptor signaling related to obesity plays an important role in the development of breast, colon and endometrial cancer." (PMID 31440472, 2019). "Leptin, which is the obesity gene product, participates in the control of body weight by regulating food intake and energy expenditure and, as a key hormone in energy homeostasis, also regulates neuroendocrine function, including reproduction." (PMID 31694146, 2019). "The effects of obesity on adipocytes include upregulation of pro-inflammatory adipokines such as leptin and resistin, downregulation of anti-inflammatory adipokine, and also the stimulation of pro-inflammatory cytokine production by macrophages." (PMID 31316526, 2019). "IKKβ/NF-κB and ER stress promote each other during HFD intake, induce leptin resistance by up-regulating SOCS3, and promote the energy imbalance underlying obesity." (PMID 31739649, 2019). "In contrast, consistent evidence indicates that leptin is an initiator for systemic and local inflammation in obesity." (PMID 31311115, 2019). "An analysis of the gene expression profile of the four groups of ASCs revealed obesity induced alterations in several key genes, including leptin (LEP)." (PMID 31013744, 2019). "Therefore, a better knowledge of the molecular mechanisms that mediate leptin action may be helpful to understand the underlying processes which link obesity to breast cancer in post-menopausal women, as well as the possible role of leptin in the response to immunotherapy in obese patients." (PMID 31380268, 2019). "Increased levels of leptin accompanied by central leptin resistance in obesity lead to increased food intake, decreased energy expenditure, and further rise in leptin levels." (PMID 31404407, 2019). "There is a direct correlation of circulating leptin levels with body fat mass; starvation or malnutrition leads to low serum concentrations, while obesity increases leptin serum levels." (PMID 31569348, 2019). "Overproduction of leptin and reduction of adiponectin were thus previously identified during obesity and are recognized to be partly involved in insulin resistance." (PMID 31215461, 2019). "The discovery of leptin took a completely different path, beginning with the study of a monogenic model of severe mouse obesity." (PMID 30357355, 2019). "Contradicting effects on different cell types and in different disease substrates have been described when evaluating leptin physiology and comparing health and disease states, since obesity induces an organ-specific leptin resistant state." (PMID 31694146, 2019). "Leptin is a hormone produced by adipocytes and was originally identified as a gene related to obesity in mice." (PMID 31447640, 2019). "During obesity development, physiological function of augmented adipose tissue is altered leading to increased adipokines secretion such as leptin and TNF-alpha." (PMID 31528182, 2019). "Leptin and obesity also promote Th17 differentiation, and Th17 cells are elevated in the visceral adipose tissues and peripheral blood of obese individuals." (PMID 30978945, 2019). "Reduction of cardiac ANP and BNP with obesity has been reported in rodents, with leptin described as a key modulator of the anti-hypertrophic effects of ANP in male mice." (PMID 31842996, 2019). "Increased leptin concentrations and a strong correlation between leptin, obesity and HOMA-IR have also been documented in studies, enrolling both classic and NC CAH patients." (PMID 31031703, 2019). "An association between leptin and CAV-1 has been provided, suggesting an important role for CAV-1 in obesity and type 2 diabetes mellitus development." (PMID 31500090, 2019). "In human and animal obesity, the secretion of leptin and other hormones from the adipose tissue appears to determine the dysregulation of the immune response." (PMID 31091785, 2019).